TLR9 (toll like receptor 9)
Diseases named in the same sentence as TLR9 in open-access papers (continued):
Sharing a sentence is not in itself a finding about the gene and the disease.
lupus (continued). "The same research group subsequently demonstrated that the manifestations in TLR9−/− mice that showed exacerbated lupus symptoms depended on TLR7, and that TLR9 inhibited the autoantibody production that was dependent on TLR7." (PMID 30103522, 2018). "In rheumatoid arthritis and systemic lupus erythematosus, hydroxychloroquine has been suggested to mediate its anti-inflammatory action by inhibiting the activation of TLR7 and TLR9 that reside in endosomal/lysosomal compartments." (PMID 30002366, 2018). "Ligation of CD180 inhibits TLR7- and TLR9-mediated activation of macrophages and DCs through the Lyn-SHP-1/2 axis, and subsequently relieves the lupus-symptoms of lupus-prone mice." (PMID 30498494, 2018). "In terms of their functions, in lupus-prone mice, TLR7 and TLR9 have opposing roles in inflammation: TLR9 is required for inflammatory regulation but TLR7 promotes lymphocytes activation and serum IgG production." (PMID 30131810, 2018). "For example, TLR7 and TLR9 sense not only pathogen-derived nucleic acids, but also self-derived nucleic acids in noninfectious inflammatory diseases such as systemic lupus erythematosus (SLE) or hepatitis." (PMID 29988708, 2018). "In this study, we asked the question if exogenous KKS decreases the IFN responses induced by either TLR (TLR7 and TLR9) or direct IFN-α stimulation in normal and lupus-prone mice, as well as in human PBMCs." (PMID 29456540, 2018). "Consistent with previous studies in lupus models, treated animals displayed reduced expression of TLR1, TLR2, TLR3, TLR4, and TLR9 in salivary tissue." (PMID 30671484, 2018). "We, therefore, used ligands against TLR7 (R848) and TLR9 (CpG-A and -B) and also directly stimulated cells with recombinant IFN-α to test if the ISGs’ expression was modulated by BKs in normal and lupus-prone mouse DCs." (PMID 29456540, 2018). "Importantly, enhanced cytokine production by pDCs was elicited not only by synthetic ligands of TLR7 or TLR9 but also by natural ligands such as self nucleic acid-containing immune complexes present in the sera of systemic lupus erythematosus (SLE) patients." (PMID 28239379, 2017). "Our aim is to study the existence of the TLR9/TGF-β1/PDGF-B pathway in healthy humans and patients with systemic lupus erythematosus (SLE), and to explore its possible involvement in the pathogenesis of lupus nephritis (LN)." (PMID 28356164, 2017). "Since pDCs are essential for lupus like disease development in mice, we next examined the expression of CD40 and CD80 on the surface of pDCs following stimulation with TLR9 agonist (CpG)." (PMID 27232337, 2016). "The second question is which TLR, TLR9, or TLR7 is critical for the role of pDC in lupus pathogenesis." (PMID 27034965, 2016). "In particular, immune complexes containing the lupus autoantigen U1snRNP or nucleosomes activate DCs and autoreactive B cells via TLR7 and TLR9, respectively." (PMID 27148268, 2016). "Other studies have examined the chimeric mice with the bone marrow of TLR9−/− MRL-Faslpr/lpr mice and TLR9−/− Jh−/− MRL-Faslpr/lpr mice to evaluate the B cell-intrinsic TLR9 signal in lupus process." (PMID 26068236, 2015). "Accelerated lupus pathogenesis in TLR9−/− C57 background mice was reported, in which mild ANA production with overactivated TLR7 signal in TLR9−/− B cells is observed." (PMID 26068236, 2015). "Very interestingly, it is now apparent that hydroxychloroquine, a mainstay in lupus treatment, is a TLR-7 and TLR-9 antagonist." (PMID 26579125, 2015). "Activation of TLR7 and TLR9 by endogenous RNA- or DNA-containing ligands, respectively, is thought to contribute to the complicated pathophysiology of systemic lupus erythematosus (SLE)." (PMID 25695778, 2015). "In the current study, a comprehensive analysis was performed to assess the capacity of B cells from SLE patients to respond to TLR9 stimulation in terms of proliferation, activation, and cytokine production in relation with clinical lupus activity using SLEDAI." (PMID 25385499, 2014).
lupus (continued). "Common TLR-9 alleles with a frequency higher than 5% however do not appear to contribute significantly to the genetic risk involved in susceptibility to SLE or lupus nephritis." (PMID 23472199, 2013). "Treatment of lupus-prone mice with a dual inhibitor of TLR-7 and TLR-9 was found to lead to the reduction of autoantibody production and amelioration of disease symptoms." (PMID 22312407, 2012). "This ODN is a very potent TLR9-antagonist in both human and mouse settings in vitro as well as in the MRL-Fas lpr/lpr strain of lupus in vivo." (PMID 20490286, 2010). "Moreover, refinement of the palindromic structure to generate combined selective TLR7/TLR9 inhibitors together with anti-B-cell-depleting protocols to re-establish critical B-cell differentiation checkpoints may result in better treatments for human lupus." (PMID 19476613, 2009). "This is relevant because DNA and RNA in the major lupus autoantigens, nucleosomes and RNP, can stimulate APCs via TLR-9 and TLR-7 pathways, respectively." (PMID 19405952, 2009). "In MRL/lpr mice with TLR9K51E, a TLR9 point mutant lacking ligand binding, lupus was ameliorated compared to TLR9 knockout mice, which was ligand and MyD88 independent." (PMID 39960645, 2025). "Therefore, TLR7 and TLR9 signals and IL-21 and IFN-γ play critical roles in ABC differentiation in lupus mice." (PMID 39960645, 2025). "More recent work revealed that in lupus mice that lacked Tlr9 systemically, conditional ablation of Tlr7 in B cells ameliorated disease." (PMID 39310226, 2024). "Agonist stimulation through TLR4 (using LPS) and/or TLR9 (using CpG) has been shown to reduce symptoms of diabetes, EAE, and arthritis in mice, while decreased TLR9 expression in humans leads to an increased incidence of systemic lupus erythematosus." (PMID 37731503, 2023). "We have previously shown that in lupus-prone MRL/lpr mice, dual-κ B cells mount enhanced antibody responses to a T cell-dependent immunization when compared to single-κ B cells, a difference amplified in the presence of the TLR9 agonist CpG." (PMID 35185888, 2022). "Nevertheless, anti-TLR9 antibody administration did not ameliorate lupus disease, suggesting that TLR9 is dispensable for disease progression in NZBWF1 mice." (PMID 36389822, 2022). "Here, we show that the anti-mouse TLR7 mAb, but not anti-TLR9 mAb, protected lupus-prone NZBWF1 mice from nephritis." (PMID 34868046, 2021). "Increased TLR9 expression has been reported in chronic infectious and noninfectious inflammatory diseases, such as systemic lupus erythematosus, cutaneous leishmaniasis, chronic hepatitis B, and acute sepsis." (PMID 33451043, 2021). "The dichotomy of TLR9 and TLR7 pathways in lupus suggests anti-dsDNA B cells and anti-ssRNA B cells may respond differently to their respective autoantigens." (PMID 30286201, 2018). "DNA and RNA are major autoAgs in lupus that can stimulate immune cells through TLR7 and TLR9." (PMID 29850618, 2018). "Numerous mouse studies also demonstrated the dichotomy of TLR9 and TLR7 in lupus pathogenesis." (PMID 30286201, 2018). "Inhibitory oligonucleotides whose guanine moiety has been modified have been found to inhibit production of Type I IFNs by human pDCs as well as pDCs from MRL/lpr mice model of lupus which were stimulated via TLR7 and TLR9 agonists, identifying another potential therapeutic route in lupus." (PMID 32185249, 2017). "Exposure to TLR9 agonist CpG-DNA (and not to TLR7 agonists) induced anti-dsDNA IgG and ICs deposition and was associated with the onset of glomerulonephritis in lupus-prone mice." (PMID 27635115, 2016). "Located at the extra-follicular clusters of both lupus-prone MRL-Faslpr/lpr mice and B6.Sle1.Sle2.Sle3 (TC) mice, RF B cells can differentiate into RF plasmablasts with the immunization of anti-chromatin IgG2aa ICs through TLR9 dependent pathway." (PMID 26068236, 2015).
lupus (continued). "Lupus-prone mice deficient in both TLR7 and TLR9 or in their adaptor protein MyD88 do not develop either autoantibodies or lupus nephritis." (PMID 26322049, 2015). "However, the discovery of TLRs in humans opened a new field in the studies of lupus, and our study of TLR3, TLR7, and TLR9 confirms their potential influence on the disease." (PMID 24692849, 2014). "Hydroxychloroquine (HCQ), a drug currently used in lupus treatment, increases cytoplasmic pH preventing acidification and maturation of endosomes while decreases pro-inflammatory cytokines production upon TLR7 and TLR9 ligation in DCs." (PMID 25229821, 2014). "A recent study conducted in a cohort of Danish SLE patients found significantly decreased TLR9 mRNA expression in lupus PBMCs, which did not correlate with dsDNA antibody titers." (PMID 25538618, 2014). "Treatments targeting TLR7/8 and TLR9 are in Phase I trials in patients with SLE and should provide insight into the role of TLR signaling in lupus including whether these therapies will be more effective in women than men." (PMID 25485543, 2014). "As dysregulated TLR signaling, particularly through TLR7 and TLR9, may contribute to lupus pathogenesis it is possible that the effects of IRF5 in lupus are mediated through alterations in the strength or nature of TLR signaling events." (PMID 25076492, 2014). "Therefore, we believe, based on our data that treatment should not only target TLR7/8 and TLR9, but also should target the effect of TLR4 signaling on lupus pathogenesis, and gender differences in other autoimmune diseases." (PMID 25485543, 2014). "Plasmacytoid dendritic cells (pDCs) constitutively express two members of the Toll-like receptor (TLR) family, TLR-9 and TLR-7, through which they can be stimulated to produce high levels of interferon (IFN)-α, a key mediator of the pathogenesis of systemic lupus erythematosus (SLE)." (PMID 22734582, 2012). "Upregulated expression of TLR-7 and TLR-9 mRNA, together with IFN-γ mRNA in PBMC, may also contribute to the pathogenesis of human lupus." (PMID 22312407, 2012). "In addition, treatment of lupus-prone mice with a dual inhibitor of TLR-7 and TLR-9 leads to the reduction of autoantibody production and amelioration of disease symptoms." (PMID 21860649, 2012). "Moreover, DNA and RNA in the major lupus autoantigens, nucleosomes and ribonucleoprotein (RNP), can act as TLR-9 and TLR-7 ligands, respectively." (PMID 19405952, 2009). "Indeed, promising results have been reported in animal models of lupus using TLR7- and/or TLR9-specific antagonists." (PMID 19476613, 2009). "TLR9 and TLR7 also had modulatory effects on clinical disease in lupus-prone mice." (PMID 18652679, 2008). "However, lupus-prone MRL/lpr mice lacking TLR9 develop more severe disease than their TLR9-sufficient counterparts, with heightened immune activation, worsened renal pathology, and increased mortality." (PMID 41178711, 2025). "Mammalian endosomal TLRs, specifically TLR7, TLR8, TLR9 and TLR3, are crucial in the development of systemic lupus erythematosus (SLE) in humans." (PMID 40976999, 2025). "The role of TLR7 in lupus pathogenesis is enhanced when the regulatory role of TLR9 is absent." (PMID 37606042, 2023). "Hence, we conclude that TLR7 promotes lupus by acting in B cells — not pDC or DC — particularly when the regulatory effect of TLR9 is absent." (PMID 37606042, 2023). "Some studies found that in the lupus-prone model, TLR9 knockdown did not improve the disease status and promoted disease progression, suggesting that TLR9 may exert a positive regulatory effect on the development of SLE." (PMID 37667233, 2023). "B-cell-intrinsic Tlr9 deficiency results in increased systemic inflammation and immune complex-related glomerulonephritis but decreased anti-nucleosome antibody levels in lupus mice, suggesting that TLR9 regulates lupus development independent of autoantibodies." (PMID 36220996, 2022).
lupus (continued). "For example, TLR2 is associated with systemic lupus erythematosus (SLE), sepsis, psoriasis; TLR3 with sepsis; TLR4 with SLE, sepsis, and psoriasis; TLR5 with psoriasis; TLR7 with SLE, stroke, and psoriasis; and TLR9 is involved in SLE, sepsis and psoriasis." (PMID 34203170, 2021). "Expression levels of TLR2, TLR7, TLR9, IFN-alpha, and LY6E (Sca-1) mRNAs in SLE patients are significantly higher than healthy controls, indicating contribution of TLR-MyD88 signaling pathways in the pathogenesis of human lupus." (PMID 31354738, 2019). "However, the absence of TLR9 in these lupus-prone models does not help improve disease conditions, but leads to disease exacerbation." (PMID 28769820, 2017). "However, in another lupus-like mouse model, anti-nucleosome antibody generation in vivo is described as depending on the expression of TLR9 unlike the production of anti-dsDNA antibodies." (PMID 31557984, 2016). "However, pDC-specific TLR7 or TLR9 deficiency in lupus-prone mice has not been reported, as B cells and some other innate immune cell types also express TLR7 and TLR9." (PMID 27034965, 2016). "Both TLR8−/− and TLR8−/− TLR9−/− mice could develop lupus phenotype by lacking their inhibitory effects on TLR7 signal." (PMID 26068236, 2015). "However, the deletion of TLR9 in these lupus-prone models did not lead to amelioration, but rather to exacerbation of disease, suggesting a protective/regulatory role of TLR9 in cells other than B cells." (PMID 25538618, 2014). "However, in systemic lupus erythematosus (SLE), endogenous nucleic acids within immune complexes containing nuclear particles reach endosomes via FcR-mediated phagocytosis before they can interact with TLR7 and TLR9." (PMID 23803655, 2013). "In one initial study with the lupus model induced by anti-DNA BCR transgene and homozygous deficiency of the inhibitory receptor FcγIIB, lack of Tlr9 was found to block class switching of autoreactive B cells to the pathogenic IgG2a and 2b subclasses with reduced pathology and mortality." (PMID 22952899, 2012). "It has become evident that RNA- and DNA-containing immune complexes, which often exist in sera of patients with systemic lupus erythematosus (SLE), can activate TLR7 and TLR9 signaling." (PMID 21396113, 2011). "On the other hand, in systemic lupus erythematosus (SLE), GRN (a degradation product of PGRN) may exacerbate immune responses and disease activity through its influence on TLR9 signaling." (PMID 41184265, 2025). "In SLE (systemic lupus erythematosus), TLR7 and TLR9 have opposing effects on disease progression." (PMID 38892317, 2024). "Thus, we hypothesized that the global absence of TLR9 may impact the way B cell–expressed TLR7 affects lupus." (PMID 37606042, 2023). "For instance, despite a positive correlation with SLE incidence, TLR9 deletion in lupus-prone mice did not reduce the severity of the disease." (PMID 37063843, 2023). "Exosomes derived from lymphocytic leukemia (CLL) can target TLR7 signaling to promote innate immunity, while exosomes isolated from systemic lupus erythematosus (SLE) patients' serum can produce abundant IFN-α, TNF-α, IL-1β, and IL-6 via the TLR1/2, TLR7, TLR9, and TLR4 pathways." (PMID 32565722, 2020). "Among the MyD88-dependent TLRs—TLR7 and TLR9 are the prominent ones involved in the development of anti-DNA Abs in mouse models of lupus and altered TLR7 and 9 expression has been reported in human SLE patients as well." (PMID 31354738, 2019). "Thus, TLR9 signaling may play a protective role in SS, similar to lupus, and activation of TLR9-dependent pathways may be a novel therapeutic strategy in SS." (PMID 30671484, 2018). "Since our earlier data showed that ligation of CD180 can negatively regulate TLR7- and TLR9-mediated activation of macrophages and DCs in vitro, we guess that ligation of CD180 may inhibit the activation of macrophages and DCs in vivo, and relieve the symptoms of lupus-prone mice." (PMID 30498494, 2018).
lupus (continued). "The data presented in this paper demonstrated that CD180, low-expressed in macrophages and DCs from SLE patients and lupus-prone MRL/lpr mice, could negatively regulate TLR7- and TLR9-mediated activation of macrophages and DCs in vivo and in vitro." (PMID 30498494, 2018). "Interestingly, the macrophage cannot induce lupus-like syndrome in the same manner, it is likely that TLR9 signal plays an important role in the ALD-DNA induced the activation of immune system and lupus model, since previous study has revealed that TLR9 is not expressed on macrophage." (PMID 29321778, 2017). "Notably, ablation of IRF4 in DKO DCs was effective in ameliorating TLR4- but not TLR9-mediated hyper-responsiveness indicating that DC dysfunction in this lupus model may encompass both IRF4-dependent and IRF4-independent pathways." (PMID 26544714, 2015). "Interestingly, TLR deficiency differentially affects lupus-specific autoantibody production, with absence of TLR7 or TLR9 reducing anti-ribonucleoprotein responses but not anti-DNA whereas lack of TLR4 reduced production of both anti-ribonucleoprotein and anti-DNA autoantibodies." (PMID 23557436, 2013). "However, in contrast the genetic ablation study carried out by Wu and Peng investigating the role of TLR9 in SLE, demonstrated that MRL mice lacking TLR9 developed more severe lupus than MRL controls, demonstrating a protective role for this gene in the pathogenesis of this condition." (PMID 23227085, 2012). "Because TLR9 signaling plays an important role in systemic lupus erythematosus (SLE), we investigated whether PGRN is involved in the pathogenesis of SLE." (PMID 23140401, 2012). "However, TLR7 and TLR9 were recently shown to have distinct effects in a murine model of Lupus and also during experimental West Nile Encephalitis, where Tlr7-/- mice, but not Tlr9-/- mice, showed an impaired CD45+ leukocyte and macrophage infiltration at the site of infection." (PMID 21253574, 2011). "Importantly, TLR9-deficiency in the non-lupus prone C57BL6 mouse background also leads to the development of a spontaneous lupus, a phenotype that has been overlooked since the lupus disease is quite milder than the one that develop lupus prone mouse models that carry various diseases elements." (PMID 36389822, 2022). "For instance, PBMCs obtained from patients with systemic lupus erythematosus that were treated with 50 nM of VitD3 express lower levels of TLR3, TLR7, and TLR9 compared to non-treated PBMCs, as observed in this study." (PMID 34634046, 2021). "In fact in the absence of TLR9, MRL/lpr mice make no anti-DNA antibodies, yet there is no mitigation of their severe glomerulonephritis; suggesting that mouse lupus does not require anti-DNA antibodies." (PMID 28955333, 2017). "In the mouse model of lupus (AM14 B cells), the BCR has RF activity and its stimulation fails to promote B cell activation (anergy) but TLR9 engagement leads to B cell activation and proliferation." (PMID 26649443, 2015). "We previously reported that serum PGRN levels are significantly elevated in systemic lupus erythematosus (SLE) patients in parallel with disease activities and that PGRN may have a role in the pathogenesis of SLE, partly by enhancing the TLR9 signaling and interleukin (IL)-6 production." (PMID 25888887, 2015). "TLR9 recognizes dsDNA with a CpG motif and, unlike TLR7, it does not accelerate disease in murine lupus." (PMID 25147296, 2014). "Thus, the absence of Tlr9 significantly accelerates the onset of glomerular renal disease and interstitial nephritis in Fas-sufficient MRL lupus-prone mice." (PMID 28278279, 2017). "In contrast, although CpG-containing DNA, which is a ligand of TLR9, is induced lupus-like disease, lack of TLR9 in the MRL/lpr mouse background exacerbated autoantibody production and disease activity, suggesting that TLR9 protects against lupus in this model." (PMID 22110541, 2012).